RNU6-608P (RNA, U6 small nuclear 608, pseudogene)
Gene: Small nuclear RNA gene on chromosome 1 (39,120,940 to 39,121,043, reverse strand). Ensembl gene ENSG00000206654.
Homologues: Orthologues: chimpanzee U6 (100% identical), macaque U6 (93% identical), guinea pig U6 (86% identical). Paralogues in human: RNU6-21P (88% identical), RNU6-468P (88% identical), RNU6-1158P (87% identical), RNU6-144P (87% identical), RNU6-33P (87% identical), RNU6-463P (87% identical), RNU6-574P (87% identical), RNU6-80P (87% identical), RNU6-1 (86% identical), RNU6-128P (86% identical), RNU6-15P (86% identical), RNU6-2 (86% identical), and 1286 more.